BDNF (brain derived neurotrophic factor)
Diseases named in the same sentence as BDNF in open-access papers (continued):
Sharing a sentence is not in itself a finding about the gene and the disease.
Cognitive impairment (continued). "The present research showed that lithium prevented cognitive impairment through reestablishment of BDNF, NGF, and GDNF expression." (PMID 29200666, 2017). "Since a decline in Arc expression is correlated with cognitive impairment in AD, BDNF-induced Arc expression fundamentally regulates the synaptic efficacy." (PMID 28265338, 2017). "Such transgenerational effects have been suggested to be mediated through epigenetic modifications, where brain-derived neurotrophic factor has been proposed as the key player in cognitive disorders." (PMID 29018327, 2017). "Physical exercise counteracts the TBI-induced cognitive deficits by elevating the brain levels of BDNF, synapsin I, and others in the cerebral ventricles." (PMID 28438174, 2017). "The idea is that cognitive deficits in AD are related to change of BDNF blood level as well as that of other neurotrophic factors such as the nerve growth factor and GDNF in blood." (PMID 28289378, 2017). "All these previous studies have suggested an involvement of both COX2 and BDNF in the pathogenesis of cognitive deficits." (PMID 28415673, 2017). "Hypermethylation of hippocampal BDNF is involved in neonatal sevoflurane exposure-induced cognitive impairments via DNMTs mediated." (PMID 28441774, 2017). "As a potent activator for exacerbating neuroinflammation, IL-1β has been reported to suppress BDNF-dependent synaptic efficacy, resulting in cognitive impairment." (PMID 28265338, 2017). "Administered neural injections of a BDNF antibody exacerbated cognitive deficits assessed by a Morris water maze." (PMID 28806788, 2017). "OA can also improve the level of brain-derived neurotrophic factor in patients with cognitive impairment." (PMID 27571507, 2016). "The expression of BDNF is downregulated not only in the brains of AD patients, but also in amnesic animal models, including the scopolamine-induced cognitive impairment model." (PMID 27023569, 2016). "This study also demonstrated that treatment of RV to young mice (4-weeks old) reduced hippocampal neurogenesis and caused cognitive impairment, in association with activation of AMPK and inhibition of p CREB and BDNF in the hippocampus." (PMID 27334554, 2016). "Here we found that the juvenile offspring of poly(I:C)-treated mice showed cognitive deficits, as well as reduced BDNF-TrkB signaling in the prefrontal cortex (PFC)." (PMID 27824119, 2016). "Neural stem cell implantation in the triple transgenic AD mice (3xTg-AD) that harbor mutated human APP, tau, and PS1, has been reported to rescue cognitive impairment via increased brain derived neurotrophic factor (BDNF) expression." (PMID 27400746, 2016). "Previous studies have demonstrated that a single isoflurane exposure induces a reduction in BDNF transcription and cognitive deficits in adult rats." (PMID 27898690, 2016). "Hormonal and BDNF levels were affected by the chronic stress of caregivers and were partially related to their cognitive impairments." (PMID 27706235, 2016). "Escitalopram treatment in patients with MNCD-AD and ScVMNCD led to an increase in plasma BDNF concentrations and, as a result, to a decrease of cognitive deficits, as well as to a decrease of depressive and anxiety symptom severity." (PMID 27597800, 2016). "The protecting effect of neurotrophic factors infusions on cognitive impairments were BDNF-specific." (PMID 25849905, 2015). "Reciprocally, interventions normalizing hippocampal levels of BDNF in these mice prevent hippocampus-mediated cognitive impairments." (PMID 26190966, 2015). "In summary, we found that a cumulative genetic risk score across three genes related to cognition, brain function, and risk for dementia (BDNF, COMT, and APOE) significantly predicted late-life cognitive impairment." (PMID 26366299, 2015). "Scopolamine induced learning and memory impairments 34, while administration of the BDNF peptide attenuated the cognitive impairments." (PMID 26463268, 2015).
Cognitive impairment (continued). "High-fat diet-induced dysfunction of insulin signaling in rats reduces expression of brain-derived neurotrophic factor (BDNF) and leads to cognitive impairment." (PMID 26658276, 2015). "A recent study showed that spicatoside A, derived from the extract of L. platyphylla, can upregulate the mRNA levels of BDNF in mice and facilitate recovery from cognitive impairment." (PMID 26075266, 2015). "In humans, BDNF mRNA and protein are decreased in the cortex and hippocampus in mild cognitive impairment (MCI) and AD and are also decreased in cognitive decline." (PMID 26464952, 2015). "Chronic unpredictable stress-induced cognitive deficits in rats were treated with cucurmin; the treatment led to a recovery of BDNF and ERK1/2 levels in the hippocampus." (PMID 26075266, 2015). "The results suggest that GA reduced cognitive deficits by reestablishing an optimal microenvironment such as increasing expression of the brain-derived neurotrophic factor (BDNF) and modulating the Th1/Th2 cytokine balance in the hippocampus." (PMID 26391515, 2015). "Huperzine A attenuates cognitive defects in streptozotocin-induced diabetic rats by increasing the levels of ChAT, BDNF, SOD, glutathione peroxidase, and catalase while simultaneously inhibiting AChE, MDA, CAT, NF-κB, TNF-α, IL-1β, IL-6, and caspase-3." (PMID 26075266, 2015). "Our data suggest that in conditions of chronic and moderate ethanol intake, the chromatin remodeling leading to BDNF signaling upregulation is an adaptive process engaged via epigenetic regulations, to limit the cognitive impairments generated by ethanol." (PMID 26670281, 2015). "Among the neurological disorders affected by cognitive deficits, PD is interesting because the neuronal pathways affected are involved in some cognitive functions that respond to the action of BDNF." (PMID 26441580, 2015). "With this in mind, the present study was aimed at exploring the relationship between BDNF serum levels and cognitive functioning in PD patients with mild cognitive impairment (MCI)." (PMID 26441580, 2015). "In conclusion, this pilot study showed that a cognitive rehabilitation program focused on the training of executive functioning improves cognitive functions and increases BDNF serum levels in PD patients with mild cognitive impairment." (PMID 25852518, 2015). "Recent studies demonstrate that decreased peripheral BDNF levels are consistently related to disease activity and progression in bipolar disorder as well as to the cognitive impairment seen in patients following their first psychotic episode." (PMID 24593295, 2014). "Augmenting BDNF/TrkB signaling has been demonstrated to be a promising strategy for reversing cognitive deficits in preclinical models of Alzheimer disease (AD)." (PMID 24614170, 2014). "Reciprocally, anti-inflammatory interventions in DIO mice reduce body weight, normalize hippocampal levels of BDNF, and prevent hippocampus-mediated cognitive impairments." (PMID 24860551, 2014). "It has also been reported that HupA can attenuate the impairment of cognitive deficits following cerebral ischemia and reperfusion in mice via promoting BDNF production." (PMID 24857910, 2014). "Future studies are required to further investigate the correlation between LPS-induced cognitive impairment and BDNF expression." (PMID 24520281, 2014). "Further, in individuals with AD or mild cognitive impairment (MCI), BDNF messenger ribonucleic acid (mRNA) is reduced substantially in the hippocampus and temporal lobe, with the extent of BDNF loss associated with the magnitude of cognitive impairment." (PMID 24475133, 2014). "For example, a SNP at position 196 (G/A) of the human brain-derived neurotrophic factor gene dysregulates protein processing and secretion and leads to cognitive impairment." (PMID 23964269, 2013).
Cognitive impairment (continued). "Overall, the results of our study limited the usefulness of BDNF as a biomarker for specific forms of dementias and, instead, support the involvement of BDNF in common pathogenetic mechanisms in all cognitive disorders analyzed." (PMID 24024214, 2013). "It has been demonstrated that BDNF signaling, through TrkB, is involved in the pathophysiology and cognitive deficits of AD." (PMID 23900282, 2013). "A recent study also supports the role of BDNF signaling through TrkB in the pathophysiology and cognitive deficits of AD." (PMID 23900282, 2013). "In contrast to the variability of BDNF levels, cognitive impairments are more stable in patients with psychosis." (PMID 23320462, 2013). "As the effect of different doses of caffeine on cognitive impairment and the expression of hippocampal BDNF and TrkB in PS1/APP mice have been poorly investigated, the present study was conducted." (PMID 23900282, 2013). "Other investigations have found positive relationships between BDNF levels and cognition in patients with diseases that result in cognitive impairment." (PMID 23320462, 2013). "The neurodevelopmental and cognitive deficits of the 3HI pups were mild and temporary, likely related to the changes in hippocampal protein expressions of BDNF and NSP-A." (PMID 23043431, 2012). "As with NGF, BDNF therapy in animals by infusion or viral transfer seems to successfully ameliorate cognitive impairment." (PMID 22654716, 2011). "One clinical study suggested that patients with AD have low whereas those with mild cognitive impairment (a stage preceding clinical dementia) had intermediate BDNF levels compared to normal controls; others have suggested raised BDNF levels in early AD." (PMID 20967212, 2010). "Long-term BDNF expression in the hippocampus mitigated neuronal degeneration or loss in these AD mice, and alleviated their cognitive impairment, with no discernible effect on amyloid-β deposition or tau phosphorylation." (PMID 41480410, 2026). "Overall, APP/PS1 model demonstrates that AAVT42-mediated delivery of BDNF into the hippocampus promotes neuroprotection against Aβ-induced neurotoxicity and strengthens dendritic structure during AD pathogenesis, thus alleviating cognitive impairment." (PMID 41480410, 2026). "Our findings suggest that IF intervention significantly attenuated HFD-induced cognitive impairment and neuroinflammation, increased BDNF levels, improved histological alterations, decreased Beclin-1 and p62 immunohistochemical expression, and upregulated LC3 and ATG5 mRNA expression." (PMID 42185381, 2026). "Furthermore, SHE administration can ameliorate cognitive impairment caused by SCO by enhancing neuron survival and synaptic plasticity through the activation of the ERK/CREB/BDNF and PI3K/Akt/GSK-3β signaling pathways in mouse hippocampus." (PMID 40949138, 2025). "Similarly, in the case of cognitive impairment, an animal model with calcitriol and physical exercise demonstrated a stronger effect on brain BDNF levels and improved cognitive performance in tests in the group combining supplementation with exercise." (PMID 40871684, 2025). "Behavioral testing confirmed significant cognitive impairment in transgenic mice, which correlated with hippocampal neuronal cell loss and injury, increased pro-apoptotic activity, and reduced expression of p-CREB and BDNF." (PMID 40430064, 2025). "Furthermore, we investigated the contribution of the BDNF/TrkB/mTOR signalling pathway to Rep lido‐induced cognitive impairment in aged mice." (PMID 41318982, 2025). "Furthermore, Gu and other researchers found that the Aβl-42 peptide caused neurodegenerative changes in a stereotaxic rat model of AD, including cognitive impairment, increased pro-apoptotic markers (Bax, caspase-3 and -9), and decreased Bcl-2 and BDNF levels." (PMID 40430064, 2025). "Further, our findings indicate that BDNF may serve as a potential biomarker for evaluating cognitive impairment in adult PWE." (PMID 40291844, 2025).
Cognitive impairment (continued). "BDNF/TrkB signaling is highly reduced in AD, resulting in cognitive impairment and synapse failure." (PMID 40380033, 2025). "BDNF/TrkB signaling is highly reduced in AD, leading to synaptic failure and cognitive impairment." (PMID 40380033, 2025). "Biochemical analyses showed that LSDF was more effective than HSDF in decreasing the serum LPS levels and increasing the BDNF levels in the cerebral cortex, which may contribute to the improvement in colitis and cognitive impairment induced by DSS." (PMID 40077572, 2025). "B. serrata gum resin limited the extent of cognitive impairment in diabetic rats and improved measures of spatial learning and memory that coincided with an upregulated expression of brain-derived neurotrophic factor (BDNF) in rat hippocampus." (PMID 41438191, 2025). "Behavioral assessments (Novel Object Recognition, Morris Water Maze) quantified cognitive impairment in scopolamine-treated mice, complemented by histological (Nissl staining, BDNF IHC), biochemical (ACh, AChE, BChE), and molecular (BDNF, CREB) analyses of hippocampal and cortical tissues." (PMID 41007261, 2025). "BDNF is more effective than CNTF in ameliorating cognitive impairment." (PMID 40380033, 2025). "Theragra chalcogramma and oat protein-derived peptides could alleviate cognitive deficits by enhancing BDNF signaling, accompanied by suppression of neuroinflammation." (PMID 40509464, 2025). "For instance, HFD decreased brain-derived neurotrophic factor (BDNF) levels in the cortex along with cognitive impairments, which could bias GR phospho-signalling toward the S226-dependent pathway." (PMID 40527010, 2025). "Therefore, further studies should evaluate the translational potential of observed BDNF alternations as blood-based biomarkers for clinical diagnosis and monitoring of dementia, as well as the possible usefulness of BDNF replacement in cognitive disorders." (PMID 41009553, 2025). "OCN binds to GPR158, activating the IP3R and retinoblastoma-associated protein 48 (RbAp48) pathways to upregulate BDNF expression, enhance BDNF-enriched vesicle transport, and increase action potential frequency and LTP in the MF pathway, thereby improving cognitive deficits in aged mice." (PMID 40337551, 2025). "They demonstrated that electroacupuncture at the Baihui acupoint, which is used in China for clinical therapy of cognitive impairment, prevented cognitive decline and neuronal apoptosis while restoring the balance of BDNF/proBDNF and TrkB/p75NTR in the hippocampus." (PMID 40430064, 2025). "Furthermore, BDNF levels are decreased at the mild cognitive impairment (MCI) stage of the disease and are correlated with cognitive functions." (PMID 40426267, 2025). "Indeed, pharmacological inhibition of HDACs was shown to increase H3/H4 acetylation and expression of BDNF, SYP, and PSD-95, and alleviate cognitive deficits associated with T2D." (PMID 41277875, 2025). "SSIRs, drugs that enhance 5-HT and endogenous BDNF expression, may prevent cognitive impairment after TBI by upregulating BDNF expression in the brain." (PMID 40149758, 2025). "Therefore, our study compared the effects of functional and aerobic training on cognitive function, serum BDNF levels, and functional fitness in older women with mild cognitive impairment." (PMID 41018016, 2025). "Moreover, BDNF upregulation by BCP has been recently reported in preclinical models of cognitive impairment." (PMID 40649806, 2025). "Similarly, another investigation highlighted a correlation between lowered serum BDNF levels and cognitive deficits in MCI patients." (PMID 40291844, 2025). "Lurasidone has been shown to modulate BDNF expression at both mRNA and protein levels in the prefrontal cortex and hippocampus, suggesting a neuroprotective role that could ameliorate cognitive deficits in schizophrenia." (PMID 40141736, 2025).
Cognitive impairment (continued). "In PBC, where cognitive impairment and fatigue are prevalent, such mechanisms, together with potential alterations in BDNF signaling within the CNS, may contribute to neurocognitive symptoms, although this relationship remains to be clarified." (PMID 40806277, 2025). "Our results showed that an NOBM could increase BDNF expression, regulate astrocyte counts and improve cognitive impairment in VD mice." (PMID 40337954, 2025). "Indeed, neuroinflammation decreases cortical BDNF expression and contributes to the occurrence of cognitive impairment in schizophrenia." (PMID 41010622, 2025). "Our findings suggest that the metal-containing PM2.5-induced synaptic dysregulation and cognitive impairment may occur through the BDNF/TrkB/p-CREB signaling pathway and the cholinergic system." (PMID 41516109, 2025). "Furthermore, its intracerebroventricular injection attenuates cognitive impairment and restores the levels of BDNF in Aβ42-injected mice." (PMID 40266679, 2025). "BDNF, pro- and anti-inflammatory cytokines may represent candidate biomarkers for cancer-related cognitive impairment." (PMID 41155372, 2025). "Furthermore, the severity of cognitive impairment in both Alzheimer’s Disease (AD) and MCI patients was found to be linked to lower serum BDNF levels." (PMID 40291844, 2025). "Therefore, active engagement in physical activity is crucial for preserving and improving QoL.Exercise improves QoL in patients with cognitive impairment by promoting neurogenesis and neurorestoration, enhancing BDNF expression, and increasing vagal tone." (PMID 41334084, 2025). "Therefore, it has been demonstrated that upregulation of the BDNF/TrkB system is effective against the cognitive impairment of mental illnesses." (PMID 40005159, 2025). "In addition, plasma levels of BDNF are reduced in AD patients or patients with cognitive impairment." (PMID 40380033, 2025). "Moreover, animal model studies have shown that genetic knockdown of BDNF leads to severe cognitive deficits, supporting its essential role in brain function." (PMID 40572619, 2025). "Based on the effects of BDNF on memory performance demonstrated in animal models, a relationship between BDNF concentration and cognitive deficits has also been hypothesized in the context of MS as well as other neurological diseases." (PMID 39812717, 2025). "Lactobacillus gasseri NK109, Lactiplantibacillus plantarum MWFLp-182, Lactobacillus johnsonii CJLJ103, and L. lactis KC24 alleviated LPS, D-galactose, or scopolamine-induced cognitive impairment by upregulation of inflammation-mediated BDNF expression [28, 33, -35]." (PMID 40016149, 2025). "The evidence suggests that combining cytokine profiles with BDNF measurements could improve early identification of cancer-related cognitive impairment and guide targeted interventions." (PMID 41155372, 2025). "This, in turn, may lead to inadequate brain plasticity by lowering hippocampal neurogenesis through lowered BDNF levels, potentially resulting in cognitive impairments." (PMID 38787900, 2024). "As a result of this inhibition, the splicing of XBP1 and the production of BDNF would be impaired, which might contribute to worsen the cognitive deficits and the inflammatory response in 5xFAD mice." (PMID 39268577, 2024). "It has also been observed that peripheral Brain Derived Neurotrophic Factor (BDNF) levels may contribute to cognitive deficits in patients with BD." (PMID 38758506, 2024). "Dysfunctional BDNF signaling resulting from NMDA receptor activity deficits may contribute to the cognitive impairment observed in the PCP model." (PMID 39408997, 2024). "Nonetheless, factors such as obesity-related inflammation, insulin resistance, and alterations in neurotrophin signaling pathways may contribute to circulating BDNF dysregulation and subsequent cognitive impairments." (PMID 38785805, 2024).